TNF (tumor necrosis factor)
Diseases named in the same sentence as TNF in open-access papers (continued):
Sharing a sentence is not in itself a finding about the gene and the disease.
Obesity (continued). "Recently, obesity has been characterized by a low-grade inflammatory state known as inflammome, indicated by chronic increases in circulating concentrations of inflammatory markers, including pro-inflammatory cytokines (e.g., IL-6 and TNF-α) and protein C." (PMID 29497960, 2018). "The mechanism for obesity‐induced proteinuria appears to be via TNF‐α activation." (PMID 29632818, 2018). "Obesity and an HF diet are associated with low-grade chronic inflammation in many tissues, which is confirmed by increased plasma concentrations of CRP, tumor necrosis factor α (TNF-α), and interleukins." (PMID 29849871, 2018). "In addition, a plethora of published evidence demonstrates that TNF-α directly affects insulin signaling in high-fat-diet-induced obesity." (PMID 29408929, 2018). "In adipose tissue of obesity, TNF-α is found to impair the activity of PDE3B." (PMID 30154727, 2018). "These altered adipokine patterns (low circulating adiponectin and high TNF-α) indicate that the effect of obesity might become severe in the presence of hypertension and vice versa." (PMID 29636702, 2018). "Furthermore, obesity has been regarded as a condition of chronic low-grade inflammation with elevation of pro-inflammatory cytokines, including tumor necrosis factor and interleukin-6." (PMID 29288474, 2018). "Obesity and T2DM are associated with a low chronic subclinical inflammatory state, which is mediated by inflammatory mediators (e.g., TNFα, IL-6, iNOS, and C-reactive protein) produced by adipose tissue, macrophage infiltration, and insulin insensitivity in adipose tissue." (PMID 30356719, 2018). "However, TNFα mRNA expression levels by PBMC were also reported to be either similar or decreased in obesity as well as measured by RT-qPCR." (PMID 30356719, 2018). "Evidence for a chronic, low-grade inflammatory state in obesity is represented principally by marked increases in plasma levels of proinflammatory cytokines such as tumor necrosis factor (TNF)-a and interleukin (IL)-6, and proinflammatory chemokines such as monocyte chemoattractant protein (MCP)-1." (PMID 30518382, 2018). "Conversely, TNF-α depletion protects mice from obesity-induced insulin resistance." (PMID 30542257, 2018). "But the main source of IL-6 and TNF-α in obesity patients is not only from WAT." (PMID 30013512, 2018). "However, TNFα and IL-6 not only impact systemic insulin sensitivity in obesity, but also promote cancer, since these cytokines are also produced from cells of the tumor microenvironment." (PMID 30591653, 2018). "In addition to TNFα, several other pro-inflammatory cytokines are increased in obesity and contribute to the development and/or exacerbation of insulin resistance, including monocyte chemoattractant protein-1 (MCP1), interleukin-1 (IL-1), and IL-6." (PMID 29570618, 2018). "We determined that during diet‐induced obesity the TNF‐dependent prevalence of blood monocytes, and inflammatory Ly6Chigh monocytes in particular, were better predictors of indices of insulin resistance than body weight or parameters of adiposity, such as adipocyte size." (PMID 30548217, 2018). "In addition, tumor necrosis factor, tumor, adolescent obesity or diabetes, inflammation, hypertension and cell are going be the hot topics related to diabetes mellitus and obesity in the next few years." (PMID 30547805, 2018). "Nonetheless, a study performed on Iranian subjects failed to prove any correlation between TNF-α 308 G>A gene polymorphism and obesity." (PMID 30338250, 2018). "It has been reported that obesity itself may be protective in HF, because it may be a marker of nutrition and activate less tumor necrosis factor-alpha which worsens heart failure." (PMID 30550609, 2018). "Consistently, deletion of TNF-α gene in rodent models of obesity protected them from developing IR." (PMID 29614722, 2018).
Obesity (continued). "In addition to interference in immune and inflammation responses, differentiation, proliferation, and cell death, TNF-α has a role in PCOS patients with obesity, insulin resistance, hyperandrogenism, and PCOS patients with hyperandrogenism." (PMID 30134857, 2018). "In particular, TNF-alpha, which is highly expressed in skeletal muscle, adipose tissue, and plasma, is one of the main mediators of the cross-talk mechanism linking obesity to insulin resistance." (PMID 29342166, 2018). "Moreover, both MeS and obesity are characterized by the activation of several inflammatory pathways, including cytokines as Interleukin-6, Tumor Necrosis Factor-alpha, Interleukin-1 and adipokines as leptin, adiponectin and resistin." (PMID 29112985, 2017). "TNF-alpha, which is increased in obesity, may also play a key role in the link between obesity and diabetes." (PMID 29209160, 2017). "Every one of these evaluations suggests that TNF-α is a key arbitrator of insulin resistance in obesity, and it could be a target in obesity-induced insulin resistance in individuals with T2DM." (PMID 28626770, 2017). "This discovery led to the hypothesis that TNFα produced from adipocytes may relate obesity to insulin resistance as plasma TNFα levels were positively correlated with insulin resistance." (PMID 28796178, 2017). "We therefore investigated the effects of elevated inflammatory cytokine TNF-α (aging/obesity) and saturated fatty acid, palmitate (obesity) on skeletal muscle cells in the presence/absence of EPA, a-3 polyunsaturated fatty acid with proposed anti-inflammatory, anti-obesity activities." (PMID 27864687, 2017). "As in obesity, this may contribute to an increase in inflammatory mediators (TNFα and IL-6), a decrease in adiponectin, and potentially insulin resistance." (PMID 28212318, 2017). "TNF-α is also an important link between obesity and insulin resistance." (PMID 28304381, 2017). "In the context of obesity, proinflammatory cytokines, such as interleukin-1β (IL1β) and tumor necrosis factor α (TNFα), or endotoxins (LPS) from the intestine, could influence the expression of thermogenic genes in BAT cells." (PMID 28481291, 2017). "In summary, TNF-α induces adipocyte lipolysis and regulates NF-κΒ activity to initiate a vicious cycle between adipocytes and immune cells that is central to the development of AT inflammation in obesity." (PMID 29186929, 2017). "Moreover, FSH treatment decreased the mRNA levels of a major mediator of obesity-related inflammation, TNF-a, which promotes inflammatory processes and induces insulin resistance." (PMID 28248545, 2017). "This 50 kDa adipokine was first discovered in a rat model when identifying genes that were differentially expressed during the development of obesity and type 2 diabetes; vaspin level is low in obesity and suppresses leptin, TNF-α, ICAM, and resistin synthesis." (PMID 28490838, 2017). "Moreover, we specifically examined the role of tumor necrosis factor-α (TNF-α), an important proinflammatory cytokine associated with obesity and a possible modulator of the Wnt pathway." (PMID 28402277, 2017). "The breakthrough description of elevated tumor necrosis factor α (TNFα) levels in adipose tissue of obese individuals and the contribution of TNFα to the establishment of insulin resistance paved the way for the concept of an inflammatory component of obesity." (PMID 29163542, 2017). "The proportion of patients treated with infliximab, which in contrast to the other anti-TNF agents is dosed in a weight-dependent manner, was similar for the different BMI categories (22%, 20%, and 25% for normal weight, overweight, and obesity, respectively; overall p = 0.57)." (PMID 28724442, 2017). "Moreover, DUSP5 mRNA expression increased during obesity development concomitant to increases in TNFα expression." (PMID 29018280, 2017).
Obesity (continued). "Alternatively, it is possible that other cells, albeit less numerous, would secrete more TNFα than macrophages and this secretion could be modulated by obesity." (PMID 28800775, 2017). "Therefore, the potential mechanisms about the effect of exercise training in diseases condition (e.g., Obesity, diabetes type 2, sedentary, and others), which modulates the production of TNF-α by increasing IL-10." (PMID 29163201, 2017). "With obesity, PTX3 mRNA expression is elevated in adipose tissue and is positively associated with the mRNA expression of the proinflammatory cytokines interleukin-1 beta (IL-1β) and tumor necrosis factor alpha (TNF-α)." (PMID 28400677, 2017). "Since obesity is a chronic inflammatory state, elevated urinary TNF-alpha might be used as a non invasive tool to monitor the level of that inflammation." (PMID 28344817, 2017). "These include obesity-related differences in tumor necrosis factor (TNF-α), interleukin-10 (IL-10), leptin, sympathetic nervous system responses, renin-angiotensin responses, the detoxification of lipopolysaccharides, and circulating atrial natriuretic peptides." (PMID 29216243, 2017). "These elevations in cardiovascular risk factors during pregnancy are further worsened in clinical states such as gestational diabetes, pre-eclampsia or obesity, which are associated with a poorer lipid profile, insulin resistance and elevated high-sensitivity CRP, IL-6 and TNF-α." (PMID 28193219, 2017). "iNOS and TNF-a were required for obesity-induced insulin resistance in mice." (PMID 29214018, 2017). "IL-6 is another cytokine, similar to TNF-α, overexpressed in the adipose tissue in obesity." (PMID 28182687, 2017). "Similarly to PS, subclinical inflammation induced by obesity is characterized by increased production of inflammatory cytokines IL-6 and TNF-α and higher C-reactive protein (CRP) levels." (PMID 28947858, 2017). "Obesity and adipogenesis could increase production and secretion of proinflammatory cytokines such as TNF‐α, IL‐1β, and IL‐6 from macrophages into adipose tissues." (PMID 28572933, 2017). "This may explain why prenatal exposure to TNF-α produces obesity, and obese children and adults have high levels of IL-6 and TNF-α." (PMID 28824543, 2017). "Obesity is associated with chronic low-grade inflammation of white adipose tissue (WAT), in which there is upregulated secretion of the pro-inflammatory cytokines TNF-α, IL-1β and IL-6." (PMID 27840174, 2017). "While most adipokines are upregulated in obesity and promote inflammatory responses (e.g., Leptin, TNFα, IL-6, and IL-18), others may act as anti-inflammatory modulators (e.g., adiponectin, and secreted frizzled related protein 5)." (PMID 28758929, 2017). "Inflammation in general also negatively affects adiponectin synthesis as TNFα suppresses the transcription of adiponectin in 3T3-L1 adipocytes, which might explain the lower adiponectin mRNA levels in obesity." (PMID 28758929, 2017). "In addition to its effects on inflammation, TNFα has detrimental effects on insulin sensitivity, and a TNFα knockout mouse is protected against obesity-induced glucose intolerance and hyperinsulinemia." (PMID 28646079, 2017). "Increased values of TNF-α were observed in our obesity model." (PMID 28265495, 2017). "TNF-α may induce insulin resistance through direct effects on the insulin signaling pathway, and thus participates in the pathogenesis of type 2 DM and obesity." (PMID 28426801, 2017). "In experimental models, it has been reported that obesity and excessive nutrition alters the inflammatory response, with increasing concentrations in TNF- α, IL1b, and IL-6, among others, resulting in the development of insulin resistance and excessive fetal growth." (PMID 28749954, 2017). "In summary, the present study showed that obesity created a low-grade chronic inflammatory microenvironment in the mammary tissue of women, as indicated by the elevations of several inflammatory cytokines, including TNF-α, IL-6, and IL-1β." (PMID 28402277, 2017).
Obesity (continued). "But, in general, decreased concentrations of PUFAs may enhance TNF-α production and this may produce neuronal damage leading to the onset of hypothalamic dysfunction and obesity and type 2 DM." (PMID 28824543, 2017). "MLD incorporated with dietary restriction and exercise treatment exhibit effects in alleviating high-fat diet-induced obesity, hyperglycemia, hyperlipidemia, hypertension, hepatic injury and insulin resistance, which are possibly due to the down-regulation of TNF-α, leptin and PKB." (PMID 28241808, 2017). "Here, we have shown for the first time that blockade of hepatocyte-associated NF-κB activation by MnP was able to ameliorate the obesity-mediated T2D phenotype, by diminishing the levels of TNF-α, MCP-1, and iNOS, which are major inducers of NASH and insulin resistance." (PMID 29104232, 2017). "It has been demonstrated that blocking TNF-α and its receptor in animal models leads to resistance to development of obesity-induced insulin resistance and it may have related benefits." (PMID 28182687, 2017). "Adipose tissue secretes a variety of biologically active factors, including the anti-inflammatory adipokine adiponectin, which is reduced in obesity, and proinflammatory cytokines such as tumor necrosis factor (TNF)α and interleukin (IL)-6, which are increased in obesity." (PMID 28929125, 2017). "In addition, choline deficiency is associated with increased levels of several inflammatory markers that link obesity to obesity-associated diseases, including CRP, homocysteine, IL-6, and TNF." (PMID 28403191, 2017). "Tlr2 expression is increased in visceral adipose tissue in mice fed a high fat diet (HFD) compared to a normal chow diet, resulting in tumor necrosis factor alpha (TNF-α) expression, thereby supporting a low grade inflammation in tissues that is typical of obesity." (PMID 29163467, 2017). "Obesity may counteract this compensatory mechanism because the raised levels of TNF-α and IL-6 in obesity suppress ADIPO production by adipose tissue." (PMID 28947858, 2017). "Similarly, high concentrations of IL-6 and TNF-α have been reported in the metabolic states of sarcopenia, obesity, and SO." (PMID 28677652, 2017). "Obesity-induced inflammatory changes in white adipose tissue (WAT), which caused dysregulated expression of inflammation-related adipokines involving tumor necrosis factor-α and monocyte chemoattractant protein-1, contribute to the development of insulin resistance." (PMID 28168013, 2017). "In addition, obesity is characterized by higher TNF-α and IFN-γ levels in plasma and in adipose tissue, and there is a reduction of these concentrations with weight loss." (PMID 29088831, 2017). "Furthermore, some evidence indicates that TNF-α is an important player in the state of insulin resistance observed during obesity by interfering with insulin signaling." (PMID 28408969, 2017). "TNF-α levels were elevated in both obesity and metabolic syndrome." (PMID 27764100, 2016). "Obesity is a state characterized by a massive infiltration of adipose tissue by macrophages, the activity of which contributes to insulin resistance by the excessive release of pro-inflammatory cytokines such as TNFα or IL-6." (PMID 27983705, 2016). "In the other hand, a low dose of icv TNFα, mimicing some of the features of low-grade/obesity-like hypothalamic inflammation, reduced UCP1 and PGC1α expression and inhibiting mitochondrial biogenesis in the BAT and resulted in reduced O2 consumption/CO2 production." (PMID 26903879, 2016). "Obesity-related elevation of TNFα may also be connected with the development of hyperleptinemia in obese subjects, because of leptin stimulation by TNFα." (PMID 27983705, 2016). "Skeletal muscle activities are inversely related to obesity because obesity accelerates muscle atrophy and decelerates muscle strength via regulating the activities of TNF-α, Ang II, AGEs, Myostatin, exogenous GC, IL-6, I/IGF, vitamin D, Ca2+, estrogen, testosterone and leptin." (PMID 27746742, 2016).
Obesity (continued). "In addition, the levels of mRNA of TNF-α are increased in adipose tissue of several murine models of obesity and diabetes and obese patients, linking such increase with the development of insulin resistance." (PMID 27766104, 2016). "Obesity is characterized by the expression of elevated levels of proinflammatory cytokines and chemokines like TNF-α, IL-1, IL-6, and MCP-1, and these factors have adverse effects on the differentiation and activation of osteoblasts while having supportive effects on osteoclasts." (PMID 27746742, 2016). "Obesity and T2DM, which are associated with insulin resistance, have been shown to have fat cell dysfunction that results in the production of an excessive amount of proinflammatory adipokines such as IL-6 and TNF-α." (PMID 27379252, 2016). "Low level elevations of gut derived endotoxin (lipopolysaccharide (LPS)) have been shown to play an important role in obesity, similarly to the consequential production of proinflammatory cytokines (such as interleukin-6 and tumor necrosis α (TNFα)), resulting from LPS-induced TLR4 activation." (PMID 27763558, 2016). "IL-6 and TNF-α, which can be elevated in obesity and insulin resistance, have been confirmed to inhibit endothelial-dependent vasodilatation, and the degenerative endothelial vasodilatation in response to IL-6 and TNF-α can result in the reduction of NO availability." (PMID 27616738, 2016). "Serum levels of TNF-α were elevated in both obesity and T2DM." (PMID 27764100, 2016). "TNF-α+ ATMs were increased at first and then decreased during the progression of obesity." (PMID 27031964, 2016). "In obesity, elevated levels of proinflammatory cytokines, such as TNFα, stimulate MCP-1 secretion." (PMID 28030645, 2016). "Thus, Arg-II-expressing macrophages facilitate diet-induced NAFLD through TNF-α and IL-6 in obesity." (PMID 26846206, 2016). "Some of these molecules secreted by adipocytes are involved in the regulation of body weight (leptin, adiponectin), in the local inflammation generated in obesity (TNF-α, IL-6, and IL-1β), in vascular function (Ang II and PAI-1), or in breeding (estrogens, among others)." (PMID 27766104, 2016). "It is a “protective” adipocytokine, involved in the regulation of glucose and lipid metabolism, as well as in inflammation inhibiting NF-κB and TNF-α production in macrophages; consistent with these data, its serum concentrations are inversely related to obesity and diabetes." (PMID 27973438, 2016). "TNFα levels are increased in subjects with obesity and T2DM." (PMID 27884163, 2016). "Certain cytokines, which are elevated in obesity such as TNF-α or IL-1α are able to induce PAR2." (PMID 28101054, 2016). "Compared to individuals with normal weight individuals with obesity have higher levels of circulating tumor necrosis factor-α (TNF-α) and interleukin-6 (IL-6), which are also secreted from adipose tissue and are involved in the pathophysiology of both obesity and periodontitis." (PMID 27590050, 2016). "The effect of the interaction between TNF-α inhibitors and statins on the various lipid parameters after adjustment for hyperlipidemia, hypertension, obesity, gender, and age reached statistical significance for LDL (p < 0.01), TC (p = 0.02), and TG (p < 0.01) values." (PMID 27832797, 2016). "Obesity is associated with adipose tissue inflammation and increased secretion of proinflammatory adipokines such as adipocyte fatty acid-binding protein (A-FABP), tumor necrosis factor-alpha (TNF-α), and interleukin-6 (IL-6)." (PMID 27819006, 2016). "What is clear however, is that one link is likely to be through increased TNF-α levels in both obesity and insulin resistance which has an apoptotic effect on skeletal muscle tissue and would in that manner, negatively impact on the function of the muscle-tendon unit as a whole." (PMID 26667010, 2016).